DUOX1 (dual oxidase 1)
Diseases named in the same sentence as DUOX1 in open-access papers (continued):
Sharing a sentence is not in itself a finding about the gene and the disease.
heart failure (1 paper, 2024). Inability of the heart to pump blood at an adequate rate to meet tissue metabolic requirements. "Future studies on animal model and primary myocardial cells should be designed to provide more insight into the biological pathways associated with DUOX1 underlying heart failure." (PMID 38750444, 2024). "The underlying mechanism of DUOX1 in regulating heart failure has been also explored." (PMID 38750444, 2024). "Meanwhile, NAC, a kind of active oxygen inhibitor, significantly reversed the level of ROS, and related factors induced by DUOX1 overexpression, suggesting a direct oxidative stress effect of increased DUOX1 expression on heart failure." (PMID 38750444, 2024). "Various studies focused on the effect of ROS on heart failure, but only few studied the role of DUOX1." (PMID 38750444, 2024). "From these, we speculated that pyroptosis may be involved in DUOX1 regulation in DOX-induced heart failure." (PMID 38750444, 2024). "In this study, we found the increased DUOX1 expression levels in DOX-induced cellular heart failure model, suggesting that DUOX1 may contribute to heart failure development." (PMID 38750444, 2024). "This study was designed to evaluate the potential role of DUOX1 in heart failure." (PMID 38750444, 2024). "Dual oxidase 1 (DUOX1) might be important in heart failure development through its mediating role in oxidative stress." (PMID 38750444, 2024). "DUOX1 inhibition in heart failure might prevent the damage induced by oxidative stress and pyroptosis, which might be a novel therapeutic biomarker for heart failure." (PMID 38750444, 2024). "Our study revealed the important role of DUOX1 in heart failure." (PMID 38750444, 2024). "In the process, oxidative stress and pyroptosis may be involved in the regulation of DUOX1 in heart failure." (PMID 38750444, 2024). "Here, we attempted to demonstrate the role and mechanism of DUOX1 in regulating DOX-induced heart failure, which may provide an evidence to identify DUOX1 as a potential therapeutic target for heart failure." (PMID 38750444, 2024). "Therefore, in order to evaluate the potential role of DUOX1 in heart failure, an in vitro model of heart failure using doxorubicin (DOX) was constructed." (PMID 38750444, 2024). "This study showed the increased secretion of IL-1β and IL-18 when DUOX1 was overexpressed in AC16 cells, suggesting that the caspase-1-dependent pyroptosis in heart failure was triggered by the upregulation of DUOX1." (PMID 38750444, 2024). "However, the role of DUOX1 in heart failure is complex and remains unclear." (PMID 38750444, 2024).
hepatitis C (1 paper, 2016). "Therefore, the expression of DUOX1, GLS2and FBP1 may change in the patients with hepatitis C and NASH." (PMID 27079415, 2016).
immunotoxicity (1 paper, 2018). "In this study, FNT induced oxidative stress by enhancing expression of NOX-2 and DUOX-1 in splenic cells stimulated with Con A, resulted in the immunotoxicity, such as inhibition of proliferation and production of T cell–related cytokines." (PMID 30513644, 2018).
laryngeal squamous cell carcinoma (1 paper, 2024). A squamous cell carcinoma that arises from the larynx. "ZC3H13 regulates the DUOX1 gene through m6A methylation modification, thereby affecting iron death in laryngeal squamous cell carcinoma." (PMID 38351022, 2024).
lichen planus (1 paper, 2014). A chronic, recurrent, pruritic inflammatory disorder of unknown etiology that affects the skin and mucus membranes. "It was noticeable the localization of DUOX1 in the plasma membrane of psoriasis and lichen planus keratinocytes and also in their cytoplasm, where it was accumulated in the upper side of these cells—that is, facing the cornified layer." (PMID 24802997, 2014). "We analyzed by immunohistochemistry 10 healthy skins and 8 lichen planus and 15 psoriasis lesions using an antibody to human DUOX1." (PMID 24802997, 2014). "Strikingly, DUOX1 was drastically induced in the skin lesions of psoriasis and lichen planus patients." (PMID 24802997, 2014). "Although this particular distribution deserves further investigation, these results strongly suggest a role for DUOX1 in psoriasis and lichen planus." (PMID 24802997, 2014). "Strikingly, DUOX1 was drastically induced in the skin lesions of psoriasis and lichen planus patients, and pharmacological inhibition of Duox1 abrogated skin inflammation, placing Duox1-derived H2O2 upstream of this inflammatory loop." (PMID 24802997, 2014). "More importantly, DUOX1 was also strongly induced in the skin lesions of psoriasis and lichen planus patients." (PMID 24802997, 2014). "In addition, DUOX1 was strongly induced in keratinocytes of human psoriasis and lichen planus patients." (PMID 24802997, 2014). "The results showed that although DUOX1 was expressed at low levels in healthy epidermis, mainly in the granular layer, a drastic induction of this enzyme was obvious in the keratinocytes of the spinous layer of the epidermis from both psoriasis and lichen planus lesions." (PMID 24802997, 2014). "The crucial role of Duox1-generated H2O2 in the infiltration of neutrophils into the skin and the induction of NF-κB prompted us to investigate if this inflammatory signal may also play a role in human psoriasis and lichen planus." (PMID 24802997, 2014).
lung disease (1 paper, 2006). "DUOX1 and DUOX2, which are expressed in lung epithelium, regulates H2O2 and acid production in the airway but have not been shown to be associated with lung disease." (PMID 16608528, 2006).
lymph node metastasis (1 paper, 2026). "Logistic regression analysis showed that the expression of DUOX1 mRNA was significantly correlated with the patient’s age, lymph node metastasis, and pathologic stage (P < 0.05)." (PMID 41556052, 2026). "The results showed that the expression of DUOX1 mRNA was significantly correlated with the patient’s age, lymph node metastasis, and pathologic stage (P < 0.05)." (PMID 41556052, 2026).
Muscular dystrophies (1 paper, 2016). "Muscular dystrophies are inherited disorders and have been associated with the overexpression of NOX2, NOX4, DUOX1, and p47phox." (PMID 27847553, 2016).
myocardial infarction (1 paper, 2024). Gross necrosis of the myocardium, as a result of interruption of the blood supply to the area, as in coronary thrombosis. "These suggest that similar function of DUOX1 are very likely reproduced in other cardiovascular disease, such as myocardial ischemia-reperfusion injury and myocardial infarction." (PMID 38750444, 2024).
neuroblastoma (1 paper, 2012). Neuroblastoma (NB) is the most common solid, extracranial childhood tumor. "Since the presence of DUOX enzymes in the brain has not been firmly demonstrated, we first have analyzed by Western blotting the expression of DUOX1 and 2 proteins in rat brain, in a stabilized human oligodendrocytes cell line (M03-13) and in neuroblastoma (SK-N-BE) cells." (PMID 22523549, 2012). "To find the role of NADPH oxidase (NOX) on DUOX1-2 expression, we first determined which NOX is expressed in neuroblastoma cells." (PMID 22523549, 2012).
non-small cell lung carcinoma (1 paper, 2013). A group of at least three distinct histological types of lung cancer, including non-small cell squamous cell carcinoma, adenocarcinoma, and large cell carcinoma. "Furthermore, investigators have demonstrated that expression of Duox1 is epigenetically silenced in non-small cell lung cancer." (PMID 23404210, 2013).
prostate tumor (1 paper, 2017). "In humans, DUOX1 is highly expressed in both normal and prostate tumor tissues, and while some patients showed higher DUOX1 expression in tumoral tissues than in normal ones, the authors did not judge that the difference was significant." (PMID 29065504, 2017).
respiratory infections (1 paper, 2023). "Because bronchial epithelial cells are one of the first lines of defense during respiratory infections, including TB, it was hypothesized that Duox1 will be protective against Mtb infection in vivo." (PMID 36936954, 2023).
Salmonella Infections (1 paper, 2017). Infections with bacteria of the genus SALMONELLA. "The NADPH-oxidase family member dual oxidase 1 (DUOX1)is involved in the zebrafish intestinal epithelial cell immune response to Salmonella infection and is also more highly expressed in salamander cells with endosymbiotic algae." (PMID 28462779, 2017).
skin inflammatory disorders (1 paper, 2014). "Our results suggest that therapies targeting DUOX1 and H2O2 could provide innovative approaches to the management of skin inflammatory disorders." (PMID 24802997, 2014).
thyrotoxicosis (1 paper, 2023). A hypermetabolic syndrome caused by the elevation of thyroid hormone levels in the serum. "The G/T genotype of DUOX1-2 (rs17595239) was significantly associated with type 2 amiodarone-induced thyrotoxicosis (AIT2) development (p = 0.0063, q = 0.0493, Cochran—Armitage trend test with Bonferroni— Šidák correction)." (PMID 36835420, 2023).
cancer (34 papers, 2013 to 2026). A tumor composed of atypical neoplastic, often pleomorphic cells that invade other tissues. "Overall, these findings suggest that EGF-induced EGFR internalization and nuclear translocation in DUOX1-deficient cancer cells is associated with altered dynamics of EGFR oxidation." (PMID 30890751, 2019). "Thus, the loss of DUOX1 found in lungepithelial cancer cells seems to be strongly associated with an invasive andmetastatic phenotype." (PMID 32453337, 2020). "In contrast, in cancer cells that lack DUOX1, abnormal dynamics of EGFR cysteine oxidation are associated with aberrant EGFR trafficking and nuclear localization, although the precise molecular mechanism(s) by which this occurs remain unclear." (PMID 30890751, 2019). "The recruitment of immune cells mediated by DUOX1 inhibits tumor growth and metastasis by phagocytosing cancer cells." (PMID 41556052, 2026). "In the luminal B subtype, which is known to grow slightly faster than luminal A cancers and to show worse recurrence-free survival at 5 years and 10 years, we observed a significant decrease in DUOX1 expression." (PMID 38542437, 2024). "The NADPH oxidase (NOX) family, which comprises seven members (NOX1–5, and DUOX1-2), is significant in the onset and development of cancer and has drawn growing attention as a significant source of ROS." (PMID 37626693, 2023). "More generally, defects in each of the players of the LoL-DDR response described here (NF-κB, PARP1, FOXO1, DUOX1 and DUOX2) share common phenotypes, such as defects in cell homeostasis and metabolism, aging and cancer predisposition." (PMID 36869180, 2023). "Collectively, our results highlight the complex crosstalk between oxidative stress and immunity in cancer and point to the relevance of DUOX1 in SKCM." (PMID 36978957, 2023). "DUOX1 silencing frequently occurs in epithelial-derived cancers and correlates with positive prognosis in certain tumours." (PMID 34804371, 2021). "Recent studies have revealed that DUOX1 suppression in cancer is driven mainly by hypermethylation of its promoter." (PMID 34804371, 2021). "Consistent with pan-cancer analysis, DUOX1 and DUOXA1 were also downregulated in LUAD from our TCGA dataset, proving their potential tumor suppression roles." (PMID 34026765, 2021). "It is conceivable that the expression and prognostic effect of DUOX1 depend on the organ and cancer type." (PMID 31706280, 2019). "Another highly interesting pathophysiological role for DUOX1 was revealed in the generation of ionizing radiation (IR)-induced thyroid cell genomic instability and cancer induction." (PMID 30084091, 2018). "The NOX/DUOX family of NADPH oxidases consists of seven members (NOX1-5 and DUOX1-2), and it has received increasing attention for its correlation with cancer development and progression." (PMID 29296219, 2017). "Additionally, the co-production of ROS by DUOX1 helps in killing cancer cells and enhancing the host’s defense." (PMID 41556052, 2026). "Conditional DUOX1 overexpression could serve to evaluate the correlation between DUOX1 silencing and cancer progression or response to therapy." (PMID 34804371, 2021). "Indeed, several studies were reported that the relationship between expression and prognostic effect of DUOX1 depend on the cancer tissue type." (PMID 31706280, 2019). "Moreover, the ability of EGF to enhance cell migration in serum-free media was observed only in DUOX1-deficient cells, consistent with previous findings linking DUOX1 silencing to increased epithelial-to-mesenchymal transition and cancer cell invasiveness." (PMID 30890751, 2019). "However, repression of DUOX1 mRNA expression significantly enriched for genes related with cancer-related pathways, including focal adhesion, extracellular matrix receptor interaction, transforming growth factor-beta signaling, and cell adhesion." (PMID 31706280, 2019).
cancer (continued). "Gene-neighbour and gene set enrichment analyses revealed that NOX1/2/5 were strongly correlated with genes associated with cancer cell survival and metastasis, whereas increased NOX4 and DUOX1 expression was associated with genes that inhibit tumour progression." (PMID 28894215, 2017). "DUOX1 silencing in H292 cells also led to enhanced resistance to epidermal growth factor receptor tyrosine kinase inhibitors such as erlotinib, and enhanced levels of cancer stem cell (CSC) markers CD133 and ALDH1." (PMID 27694834, 2016). "Thus, our novel findings might contribute to the understanding of the biology of cancers that have decreased DUOX1 expression, which could be useful to the development of future therapeutic approaches." (PMID 29849884, 2018). "Thyroid glands and thyroid cells in vitro maintain a high DUOX1 activity for many days after IR exposure controlled by interleukin(IL)-13 and mitogen-activated protein kinase (MAPK) p38, which leads to H2O2 production causing DNA strand breaks, chromosome translocation, and cancer development." (PMID 30084091, 2018). "To date, the interconnection between H2O2 signaling and EMT in cancer is well established, and the role of H2O2 producers NADPH oxidase 4 (NOX4), dual oxidase 1 (DUOX1) and DUOX2 in cell motility and metastasis in cancer biology has been reviewed." (PMID 35873564, 2022). "Among the genes corresponding to DNA methylation in the prognostic signature, we identified that ZEB1 and DUOX1 are drivers of ferroptosis and that CISD1 is a suppressor of ferroptosis, which play a crucial role in cancer development." (PMID 36555319, 2022). "Mitochondria and NOXs family, including NOX1, NOX2, NOX3, NOX4, NOX5, DUOX1, and DUOX2, are two important sources of ROS production in cancer cells." (PMID 35418176, 2022). "Mitochondria and NADPH oxidases of the Nox family including NOX1, NOX2, NOX3, NOX4, NOX5, DUOX1 and DUOX2, are two important sources of ROS production in cancer cells." (PMID 30755243, 2019). "Data from the cancer genome atlas (TCGA) have shown that cancers of epithelial origin, including skin, lung, prostate, liver, stomach, brain, head and neck, and breast, overexpress one or more NOX enzymes, particularly NOX4 and DUOX1/2." (PMID 39201571, 2024). "Moreover, its interaction with DUOX1 and DUOXA1 emphasized similar contributions to inhibit the malignant progress of cancer." (PMID 34026765, 2021). "Based on these considerations, we propose that DUOX1 activation during ligand-dependent EGFR activation may play an important role in regulating EGFR internalization and recycling, which may therefore be disturbed in cancer cells that lack DUOX1, in favor of nuclear EGFR localization." (PMID 30890751, 2019).
tumor (28 papers, 2015 to 2026). "In order to show the physiologicalconsequences of DUOX1 loss, we silenced DUOX1 in a non-tumor human mammaryepithelial cell line MCF12A." (PMID 32453337, 2020). "However, it should be noted that the association between tumor immune infiltrating cells and DUOX1 mRNA expression was based only on TCGA database analysis results, and the tumor immune infiltrating cells correlation coefficient was not high." (PMID 41556052, 2026). "In addition, zebrafish models of SKCM revealed that DUOX-1-deficient SKCMs showed reduced tumor growth, but increased metastasis compared to control SKCMs." (PMID 36978957, 2023). "In this study, the single-sample gene set enrichment analysis (ssGSEA) method was used to evaluate the correlation between DUOX1 mRNA expression and the abundance of tumor immune infiltrating cells." (PMID 41556052, 2026). "Taken together, these findings indicate that DUOX1 silencing is directly proportional to tumor severity." (PMID 41556052, 2026). "The results indicated that there was an expression difference between normal tissues and tumor tissues, with the level of DUOX1 mRNA being decreased in tumor samples (P < 0.05)." (PMID 41556052, 2026). "Consistent with our findings, a previous study reported that DUOX1 can promote reactive oxygen species (ROS) production and observed a correlation between intracellular ROS accumulation and tumor suppression." (PMID 41556052, 2026). "In cancer, DUOX1 is frequently epigenetically silenced, consistent with tumor-suppressive roles, whereas DUOX2 is often upregulated and can promote tumor progression." (PMID 40867898, 2025). "We also demonstrate the efficacy of P-AscH− and DNMT inhibitors in vivo, where tumor volume was significantly reduced and DUOX1 expression was increased in a xenograft model." (PMID 37759986, 2023). "The silencing of DUOX1 gene expression is mediated by promoter hypermethylation and DUOX1 appears to be a functional tumor suppressor involved in liver carcinogenesis." (PMID 36290761, 2022). "The analysis also showed that DUOX1 is highly expressed in tumor tissues and related to age and grade." (PMID 32843657, 2020). "In the absence of IL-22 responses in transformed ApcMin/Min cells, one likely explanation for the tumour-promoting effect of IL-22 in ApcMin/+ mice is provided by our discovery that IL-22 induces expression of iNOS and Duox1/2." (PMID 31770366, 2019). "In order to determine the model robustness for predicting prognosis of HCC patient after tumor resection, we finally resorted to ROC curve analyses by individually using the expression of each marker (DUOX1, GLS2, FBP1)." (PMID 27079415, 2016). "In order to deeply investigate the impact of DUOX1, GLS2, FBP1 and age on DFS and OAS, we developed a simple score composed of the four variables to predict the risk of HCC relapse and death after tumor resection." (PMID 27079415, 2016). "Then a multivariate analysis with Cox’s proportional hazard model manifested that DUOX1, GLS2, FBP1 and age were independent risk factors for the prognosis of HCC patients after tumor resection." (PMID 27079415, 2016). "Finally, the combination of a DNMT inhibitor and P-AscH− in vivo increases DUOX1 expression and decreases tumor volume compared to either treatment alone." (PMID 37759986, 2023). "Tumor samples were also stained for DUOX1 and immunofluorescence was quantified." (PMID 37759986, 2023). "Recent research indicates that DUOX1 may function as a selective tumor-suppressor gene (TSG) during tumor initiation and progression." (PMID 36290761, 2022). "MCF12A shDUOX1 cell line presented a higher proliferative rate and decreased adhesion, which suggests that DUOX1 may exert a tumor suppressor role." (PMID 29849884, 2018). "As such, it was concluded that DUOX1 acts as a tumour suppressor in HCC development." (PMID 28894215, 2017). "According to these data, NOX4 and DUOX1/2 exhibit a tumour suppressive function." (PMID 28894215, 2017).